CD28 (CD28 molecule)
Diseases named in the same sentence as CD28 in open-access papers (continued):
Sharing a sentence is not in itself a finding about the gene and the disease.
tumor (continued). "In contrast, anti-CD28 costimulation favoured an IL-17 phenotype only Furthermore, IFNγ+ Th17 cells developed through costimulation with ICOS ligand were superior to cells costimulated with anti-CD28 in regression of human tumour engrafted into mice." (PMID 26101460, 2015). "Altering the balance between CD28/B7 positive and CTLA-4/B7 negative regulatory signals may enhance anti-tumor immune response." (PMID 25893809, 2015). "Through whole genome and RNA sequencing (RNA-seq) of a SS patient's tumor we discovered a highly expressed gene fusion between CTLA4 (cytotoxic T lymphocyte antigen 4) and CD28 (cluster of differentiation 28), predicting a novel stimulatory molecule on the surface of tumor T cells." (PMID 25802883, 2015). "In these trials, lymphocytes [either tumor-infiltrating lymphocytes (TIL) or gene-engineered PBL] are often expanded with high dose IL-2 (6000 IU/ml) and soluble OKT3 (anti-CD3), or are expanded with magnetic beads decorated with CD3 and CD28 agonists." (PMID 24987392, 2014). "They found CAR T cells with combined CD28 and 4-1BB co-stimulatory domains and specificity for prostate-specific membrane antigen (PSMA) were superior with regards to cytokine production, in vivo survival and antigen-specific tumor elimination." (PMID 24358223, 2013). "Adoptive CD8+ T cell therapy refers to an immunotherapy approach in which tumor-infiltrating lymphocytes (TILs) isolated from tumor specimen are activated and expanded in vitro to large quantities, using anti-CD3/CD28 antibodies and IL-2, and then transferred back to the cancer patients." (PMID 23785406, 2013). "Sunitinib treatment enhances the functional capacity of tumor infiltrating T cells by stimulating IFNγ production and cytolytic activity against the tumor and improves Th1 response after stimulation of PBMC by anti-CD3/CD28 antibodies in mRCC patients." (PMID 23320019, 2012). "Crosslinking of T cell activating CD28 may be less important than blocking the inhibitory CTLA-4, since activated T cells recognizing tumor antigens require less costimulation." (PMID 24955288, 2012). "CD28-CD3ζ CAR stimulated T cells thereby indirectly increase antitumor efficacy by sustaining survival, proliferation, and recruiting other activated bystander T cells in the tumor environment." (PMID 21837241, 2012). "Moreover, the PBL cells have demonstrated, in all types of tumour diseases, an increasing expression of cell surface markers CD8+CD28+ confirming the effectiveness of “cellular therapy”." (PMID 22400112, 2012). "Unlike peripheral blood lymphocytes (PBL), most tumor antigen-specific CD8+ TILs derived from solid tumors express low levels of CD28." (PMID 21827675, 2011). "In this study, we observed that stimulation of tumor-specific CTLs with CD3 mAb in the presence of a costimulation signal from CD28 failed to maintain CTL proliferation in vitro and persistence in vivo." (PMID 21124930, 2010). "An increase in cell surface B7-1 expression breaks the immune tolerance allowing B7-1 to bind preferentially to its main receptor CD28 on antigen presenting cells (rather than Treg) creating an anti-tumour response." (PMID 21172020, 2010). "A major advantage of IL-15 and IL-21 is that they can maintain the expression of the T cell co-stimulatory molecule CD28 and lymphoid homing markers such as CD62L, which was found to improved the in vivo survival and anti-tumor activity of adoptively transferred T cells in murine model experiments." (PMID 17406677, 2007). "The implications of these findings are that, while tumor cell lysis by chimeric T cells is independent of CD28, IL-2 secretion will be lacking under these circumstances." (PMID 16507098, 2006). "Considering the metastasis progression observed in the group treated twice with CD19 CAR-T (CD3z-CD28) cells, we investigated the activation of the endogenous immune response triggered by CAR-T cells and the participation of chicken embryo immune cells in the tumor challenge." (PMID 41596451, 2026).
tumor (continued). "They found that PGE2 prevented the maturation of dendritic cells (DCs), and the activation of naive CD8+ T cells was terminated; meanwhile, the CD8+ CD28− T cells were induced, and tumor cells could not be killed." (PMID 41041304, 2025). "Our main hypothesis regarding CD20+ T-cells was that they may play a more competent role in the tumor elimination compared to CD20- T-cells which is supported by the elevated incidence of CD20+ T-cells in MGUS and MM and the expression of CD8, NKG2D, and CD28." (PMID 40079005, 2025). "However, in our IHC analysis, we detected CD28 expression only on immune infiltrates and not on tumor cells, which is consistent with previous observations of its essential role in T cell growth and survival." (PMID 41155258, 2025). "For example, if there are active immune activation signals between some tumor subpopulations and T cells (such CD80/CD28 or IFNG/IFNGR), it could mean that the patient is more likely to respond to immunity therapy and could benefit from immune checkpoint inhibitors." (PMID 40842994, 2025). "Analysis of Cd28−/− and Carmil2−/− mouse cohorts showed that both CD28 and CARMIL2 molecules were essential for antitumor rejection since their absence permitted BRAFV600EPtgs−/− tumor growth, whereas Carmil2QE mice rejected the BRAFV600EPtgs−/− tumor as efficiently as WT mice." (PMID 40402149, 2025). "CD36 also exhibited positive correlations with several immunostimulators, including C10orf54, CXCL12, ENTPD1, CD28, and TNFSF18, suggesting that it may contribute to immune activation pathways and modulation of antitumor immune responses in the tumor microenvironment." (PMID 41550652, 2025). "Additionally, PFS comparisons between patients with high and low proportions of tumor-infiltrating CD28−/CD8+ T cells using a cut-off value of 52.33% did not reveal any significant differences." (PMID 40136325, 2025). "The functional consequence of this selective gain-of-function in CARD11 recruitment in mice is to correct the majority of activation and differentiation defects caused by CD28 deficiency or by the absence of the CD80 and CD86 ligands including Treg cell development and tumor eradication." (PMID 40402149, 2025). "For example, binding of PD-1 on T cells to PD-L1 expressed on tumor cells or antigen presenting cells (APCs) would first recruit protein tyrosine phosphatase-2 (SHP2) to dissociate proximal signaling molecules downstream of the T cell antigen receptor (TCR) and CD28." (PMID 40276607, 2025). "In particular, tumor‐infiltrating T cells are typically presented with classic immunosenescent characteristics, incorporating with impaired production of cytokines (e.g., GZMB) and phenotypic changes (e.g., downregulated expression of CD28 and upregulated expression of Tim‐3)." (PMID 41427020, 2025). "Upon activation of TCR and CD28, transient phosphorylation of ZAP70 and PI3K/AKT would first occur and lead to downstream cascaded activation of ERK and NF-κB, which can promote the production and secretion of IL-2 and IFN-γ by T cells to enhance anti-tumor cytotoxicity." (PMID 40276607, 2025). "However, among stage I patients, those with LVSI had a significantly lower proportion of tumor-infiltrating CD28+PD1−/CD8+ T cells compared to those without LVSI (3.54% vs. 11.66%, p = 0.023)." (PMID 40136325, 2025). "In order to discern CTLA4 cytosolic or membrane localization, along with its ratio to CD28, we quantified and compared protein levels of CTLA4, CD28, and the ligand CD80 in the lymph nodes and in the TIME between the same patients representing specific tumor clusters." (PMID 40492347, 2025). "Although neither of these checkpoint inhibitors engage CD28 directly, their primary therapeutic mechanism is enhancement of costimulation, strongly suggesting that biologics that stimulate CD28 signaling in a tumor-targeted manner have potential as a novel class of immunotherapy." (PMID 39301613, 2025).
tumor (continued). "While the rationale for the initial incorporation of CD28 as a co‐stimulatory molecule in a second‐generation CAR for NK cells was less well‐defined, it has recently been validated to result in enhanced CAR‐NK cell persistence and sustained anti‐tumour cytotoxicity." (PMID 39763064, 2025). "However, it will be more natural and realistic to identify the impact of PPL-C on T cell activity in the tumor-bearing mouse model without anti-CD3/anti-CD28." (PMID 38745661, 2024). "Among all patients and the subgroup of patients treated with PD-1 inhibitors, CD8+CD28+ T cells and NK cells were identified as the common independent prognostic factors for PFS and OS, whereas CD8+CD38+ T cells were common independent prognostic factors for tumor response." (PMID 38404585, 2024). "The universal chimeric antigen receptor (UniCAR) second-generation 2-component platform includes a CD28 costimulatory domain, a first component, which is a CAR that recognizes a targeting module included in the second component, which confers specificity against the tumor antigen of choice." (PMID 38791898, 2024). "As anti‐CD3/CD28 antibodies activated T cells cannot specifically target tumor cells in vitro without tumor antigen presentation during their development and maturation, chimeric antigen receptor T (CAR‐T) cells were used as a model for their specific antitumor abilities." (PMID 37009412, 2023). "While this did correlate with potent cytotoxicity in vitro, the CD28-based CARs use in this study were not as effective at controlling a tumor in a rodent model as their 4-1BB-based counterpart, with the former cells becoming more rapidly exhausted and failing to persist." (PMID 37518011, 2023). "Considering the role of CD28 as main target of PD1 signaling, we may envision that this liaison can play a critical role in the different functional outcome of the two subsets at the tumor site." (PMID 37898752, 2023). "Increased expression and binding of CTLA-4 to CD28 contributes to the activation of intracellular mechanisms responsible for the immunosuppression of the cytotoxic tumour cell killing reaction by CD8+ cytotoxic cells (CTLs) and the immunotolerance of tumour neoantigens." (PMID 36980527, 2023). "Even though CD28-based CAR-T cells had similar ZAP70 activation dynamics as 4-1BB-based CAR-T cells, they displayed slightly enhanced ERK activation, which may contribute to their faster anti-tumor kinetics in vivo." (PMID 35252208, 2022). "Interestingly, a study reported that 4-1BB agonist treatment induces a subset of CD4+Foxp3+ Tregs to eliminate virus-induced tumor cells in mice, and the addition of 4-1BB expression in CAR T cells with an intracellular CD28 costimulatory domain improves their proliferation and cytotoxicity." (PMID 35917188, 2022). "To investigate whether lactic acid in tumor microenvironment elevated Vam6 expression, we treated iNKT cells with lactic acid in vitro, and found that lactic acid increased Vam6 expression in both anti-CD3 plus anti-CD28 stimulated and unstimulated cells." (PMID 36741382, 2022). "Hence, the authors developed another model by altering CD28 to determine the correlation between these two ligands by crossimplanting Foxp3creERT2 x Cd28f/f mice, which then were treated with TAM to delete CD28 in tumor-infiltrating Treg cells." (PMID 36009853, 2022). "Moreover, we found tumor-cell loss of MLL3 or MLL4 promotes survival, proliferation, and cytotoxicity of antigen-nonspecific CD8+ T cells pre-activated by anti-CD3/CD28 antibodies as well." (PMID 36323669, 2022). "To ensure our sorting purity, we compared tumor-infiltrating NK and T cell gene expression, highlighting unequivocal differences in DGE of canonical NK and T cell genes among the respective subsets, specifically NCAM1 and IL2Rb in NK cells, and CD3, CD8 and CD28 in T cells." (PMID 35874727, 2022).
tumor (continued). "Regarding the tumor weight, we observed a 30% reduction in all mice treated with anti-CAIX 4-1BB CAR T cells with or without the expression of anti-PD-L1 antibodies and a 60% reduction upon treatment with anti-CAIX CD28 CAR T cells capable of expressing anti-PD-L1 IgG4 antibodies." (PMID 35628256, 2022). "As CD28 and CD226 provide two important co-stimulatory pathways, loss of both may mark cells no longer capable of exerting anti-tumor effector function." (PMID 35263569, 2022). "Furthermore, in T cells stimulated with CD3/CD28 antibodies in the absence of tumor antigen, hypoxia remains capable of suppressing the effector expression of CD8+ and CD4+ T cells." (PMID 35840558, 2022). "Corroborating this assumption, our data show that whole platelets, as well as tumour cell-induced releasates, evoked Treg differentiation from CD3/CD28/CD2 stimulated CD4+ T cells, although further cell types than regulatory T cells might contribute to IL-10 release from PBMCs." (PMID 35285006, 2022). "Placing both CD28 and 41BB costimulatory domains upstream of CD3ζ in third-generation CAR T cells demonstrated variable results: some showed improved expansion, cytokine production and anti-tumor function, while others had inferior activity in comparison to second generation CARs." (PMID 35617812, 2022). "This is because BiTEs mediate target cell killing mainly via (non-tumor) antigen-experienced T cells that differentiate to effector memory T cells after activation and these cells can be reactivated without costimulatory signals such as CD28 and IL-2." (PMID 34885176, 2021). "We compared trafficking, expansion and tumor control for T cells expressing different CAR construct designs targeting two antigens (L1CAM or HER2), structurally identical except for spacer (long or short) or co-stimulatory (4-1BB or CD28) domains to be evaluated." (PMID 33801448, 2021). "2.5 × 104 of CD8+ T cells from peripheral bloods of NC (n = 9), peripheral bloods of GC patients (n = 11), and tumor-residency of GC patients (n = 11) were cultured for 12 h in the presence of anti-CD3/CD28 with or without Pam3Csk4, a TLR2 agonist which was used for TLR2 activation." (PMID 34620075, 2021). "It is our speculation that when stimulated by tumor antigen in the absence of CD28 signaling in the tumor microenvironment and in lymphoid tissues, CD8+ T cells upregulate the expression of CD73." (PMID 34011962, 2021). "Consequently, inhibitory antibodies were developed, such as ipilimumab, blocking CTLA-4 function and thereby facilitating positive co-stimulation with CD28 and allowing the rescue of exhausted CD8 T cells and NK cells, leading to tumor control of colon and melanoma tumors." (PMID 34572799, 2021). "To investigate whether in vivo anti-cancer potential of HER2-specific CAR T cells utilizing 4-1BB or CD28 signaling differ, we treated SKOV3 tumor-bearing Rag−/− mice by a single intravenous injection of untransduced or HER2-specific SS-4-1BB/ζ, LS-4-1BB/ζ-, SS-28/ζ-, LS-28/ζ-CAR CD8+ T cells." (PMID 33801448, 2021). "Comparison among CAR2 T cells, CD28-based CAR exhibited rapid expansion and strong effector-like function, but shorter T cell persistence whereas 4-1BB-based CAR had a superior function in promoting more memory phenotype, which prolonged anti-tumor activity of CAR T cells in vivo." (PMID 35117999, 2021). "All published relevant methods, to our knowledge, aiming at amplifying in vitro tumor-specific CTLs, including MART-1-specific T cells, are based on the use of autologous antigen presenting cells, allogeneic cells, K562-derived antigen presenting cells or anti-CD3/anti-CD28 beads." (PMID 34566953, 2021). "Consequently, mice deficient in Cbl-b have hyperactive T cells that do not require CD28 for their activation, which significantly enhances T-cell anti-tumor immunity in vivo." (PMID 34639141, 2021).
tumor (continued). "Similarly, PD‐1, a member of the extended CD28/CTLA4 family of T‐cell regulators, is expressed by activated T cells where it binds to the PD‐1 ligand expressed by tumours and APCs to inhibit T‐cell effector function, a reversible process termed T‐cell ‘exhaustion’." (PMID 33773029, 2021). "Costimulation using CD28 increased markers of activation and effector function in patient RCC TILs in a pattern similar to that observed in prior studies with preclinical and patient samples of other tumor types showing that costimulation using CD28 or 4-1BB can increase antitumor activity." (PMID 32814710, 2020). "PD-L1 CCR, which includes the CD28 costimulatory domain, can be used to design logic-gated CARs and be likely to enhance the safety profile of CAR-T cells and improve their efficacy either when the low-affinity CAR is used or the tumor cells express low-level TAAs." (PMID 33292688, 2020). "In addition, CD28 and CTLA4 expression has been reported in activated mouse NK cells, the interaction between CTLA4 and CD80 has a direct effect on IFN-γ release by NK cells, and CTLA4 expression has been reported in mouse tumor infiltrating NK cells." (PMID 31898484, 2020). "The NK-CAR-iPSC-NK cells demonstrated superior anti-tumor activity when directly compared to T-CAR-iPSC-NK cells in an ovarian cancer xenograft model and had similar activity as observed for CAR T cells that expressed a typical CAR designed for T cells (CD28-CD3ζ)." (PMID 32903482, 2020). "We also did not ligate CD28 because our aim was to identify PD-1–triggered signaling pathways that may be engaged within the tumor, and tumor cells do not express B7.1 and B7.2, the ligands for CD28." (PMID 33077516, 2020). "Interestingly, CD4+ T cells engineered with the PD1/CD28 fusion construct provided enhanced T-cell help to improve the anti-tumour activity of CD8+ T cells in a pancreatic cancer and non-Hodgkin lymphoma model." (PMID 32708397, 2020). "To determine if MDSCs inhibit the activity of T cells, we purified MDSCs from tumor tissues of cancer patients and from their PBMCs, and then we co-cultured them separately with autologous T cells at the 1:2 ratios in the presence of CD3/CD28 antibody stimulation for 72 hours." (PMID 33247701, 2020). "However, CD8+ T cells in cancer patients can lose the expression of CD28 due to the chronic stimulation of tumor antigens and consequently present with a non-responsive status to tumor antigens." (PMID 30971280, 2019). "Therefore, our aim consisted of evaluating the predictive roles of pre-SABR CD8+ T-cell counts, CD8+CD28+ T-cell counts, CD8+CD28− T-cell counts, CD4+ T-cell counts, and Treg-cell counts in peripheral blood for early tumor response to SABR in patients with lung metastases from NSCLC." (PMID 30971280, 2019). "To understand whether these infiltrated CD8+ T cells in metastatic nodules were tumor-responsive or exhausted, we analyzed the metastatic nodules for CD28 and NKG2D, co-stimulatory receptors that serve as non-exhaustion markers." (PMID 31208461, 2019). "We propose that a panel comprising the markers CD45RA, CCR7, CD95, CD69, CD57, PD-1 as well as CD28, CD40L, and ICOS should be validated in larger cohorts of patients and used to develop a model aiding in the identification of NSCLC patients prone to show tumor regression upon anti-PD-1 therapy." (PMID 31176366, 2019). "In addition, most tumor cells, especially non-hematopoietic tumor cells do not express ligands of CD28, CD80, and CD86." (PMID 31001256, 2019). "ATV-NDV tumor vaccine with attached anti-HN-anti-CD3 (αHN-αCD3) and anti-HN-anti-CD28 (αHN-αCD28) bsAb exerted in vitro, upon stimulation of allogeneic human peripheral blood mononuclear cells (PBMC), strong and durable antitumor effects against human tumor cell monolayers." (PMID 31480379, 2019).